FOXK2 (forkhead box K2)
Diseases named in the same sentence as FOXK2 in open-access papers (continued):
Sharing a sentence is not in itself a finding about the gene and the disease.
cancer (continued). "Most importantly, HCC patients presenting high FOXK2 protein expression exhibit worse survival in both uni- and multivariate analysis, pointing to FOXK2 as an independent predictor of poor prognosis in this type of cancer." (PMID 30897782, 2019). "The forkhead transcription factor FOXK2 has recently been implicated in cancer cell proliferation and survival, but a role in cancer chemotherapeutic drug resistance has hitherto not been explored." (PMID 26344694, 2015). "This review provides an overview of the recent progress in understanding the regulatory mechanisms of FOXK2 and its downstream targets, highlights the significant impact of FOXK2 dysregulation on cancer etiology, and discusses the potential of targeting FOXK2 for cancer treatment." (PMID 38741782, 2024). "Based on the analysis of two immunotherapy cohorts and the negative correlation between FOXK2 and the expression of nine immune checkpoint genes in most cancer species, our hypothesis is further validated that low expression of FOXK2 indicates better immunotherapy efficacy." (PMID 39552461, 2024). "Together, these data strongly support the hypothesis that FOXK2 regulates cancer stemness." (PMID 35349489, 2022). "Additionally, we focused on the prognostic value of FOXK2 expression in various cancers." (PMID 36172141, 2022). "Additionally, FOXK2 K223 acetylation significantly affected the expression of cell cycle–related and apoptosis‐related genes in cisplatin‐stimulated cancer cells, and FOXK2 K223 hyperacetylation promoted mitotic catastrophe, which enhanced chemosensitivity to cisplatin." (PMID 34866322, 2022). "As FOXK2 regulates DVL and Wnt/β-catenin signaling pathway, makes it a potential target for cancer progression and metastasis." (PMID 38741782, 2024). "Although the decrease in expression of FOXA1 and FOXK2 were less dramatic than FOXM1, it is likely that these effects are biologically significant, and in part account for the anti-cancer activity of NB compounds." (PMID 38704607, 2024). "FOXK2 holds promise as a biomarker for predicting immunotherapy responses in BRCA, offering the potential to assist in patient selection and refinement of cancer treatment strategies." (PMID 39552461, 2024). "Additional research is required to completely understand the mechanisms that are responsible for the participation of FOXK2 and its subsequent gene FBXO32 in cancer, as well as to explore the possible advantages of focusing on FOXK2 for cancer treatment." (PMID 39552461, 2024). "Forkhead box K2 (FOXK2), which is essential for cell fate, regulates cancer cell apoptosis through several post‐translational modifications." (PMID 34866322, 2022). "Forkhead box K2 (FOXK2) has important regulatory functions in the proliferation, migration, invasion, metastasis, metabolism and apoptosis of cancer cells." (PMID 34866322, 2022). "ERN1 expression was also significantly increased in FOXK2-OE OC (OVCAR5 and OVCAR3) and non-cancer (FT190 and NoEM) cells." (PMID 35349489, 2022). "FOXK2 is a member of the FOX family and plays many broad and distinct roles in cell proliferation, DNA damage, metabolism, and cancer progression 36-39." (PMID 34239356, 2021). "Nevertheless, the role of FOXK2 phosphorylation by CDK/cyclin complexes and other kinases on the regulation of drug resistance in cancer remains to be elucidated." (PMID 29540677, 2018). "Emerging evidence suggests that the there are several different mechanisms involved in the regulation of FOXK2 activity in cancer cell, such as hypermethylation, noncoding RNAs (ncRNAs), and post-translational modifications (PTMs)." (PMID 36172141, 2022). "As a result, FOXK2 did not inhibit apoptosis in cancer cells in the nucleus following cisplatin treatment, consistent with previous studies." (PMID 34866322, 2022).
cancer (continued). "By integrating patterns of FOX genes expression with anticancer drugs sensitivity, we speculated that six FOX genes, including FOXO3, FOXO1, FOXN3, FOXK2, FOXN2, and FOXJ3, might be important for the development and treatment of a wide range of cancers." (PMID 36292640, 2022). "Since evidence on the role of FOXK2 in human cancer has only recently emerged, there is not much data available reporting FOXK2 expression in samples from cancer patients." (PMID 30897782, 2019). "While FOXK2 interactions with these pathways have been extensively explored in the context of cancer biology, our studies in a nontumorigenic cell model highlights the broad relevance of FOXK2 in influencing these fundamental homeostatic pathways in the native state." (PMID 38735474, 2024). "Collectively, these results indicated that FOXK2 K223 deacetylation reduced cancer cell chemosensitivity to cisplatin by inhibiting cleaved‐PARP and cleaved‐caspase 3 expression and suggested that the FOXK2 acetylation status may be a prognostic biomarker in cancer chemotherapy." (PMID 34866322, 2022). "FOXK2, a member of the FOX family of transcription factors, plays a role in cancer progression, although its specific function in cancer is not fully understood." (PMID 39552461, 2024).
infection (5 papers, 2007 to 2025). The state of being infected such as from the introduction of a foreign agent such as serum, vaccine, antigenic substance or organism. "RT‐qPCR and Western blotting analyses revealed 6.6‐fold and 1.8‐fold increase in mRNA and protein levels, respectively, following infection with an adenovirus expressing Foxk2." (PMID 39789420, 2025). "The data indicate that FBXO24 overexpression and PA103 infection differentially modulate FOXK2 phosphorylation, depending on the targeted residues." (PMID 38735474, 2024). "FOXK2 disposal mediated by SCFFBXO24 during infections might be an opportunity to devise small molecule FBXO24 inhibitors that preserve FOXK2 levels." (PMID 38735474, 2024). "Hence, we focused on using heterozygous (Fbxo24+/−) mice that despite infection with K. pneumoniae showed generally preserved lung concentrations of FoxK2 and several mitochondrial markers and related function." (PMID 38735474, 2024). "Thus, although speculative, the aa 155 to 203 (Δ155–203) or the FHD motifs might be prone to site-specific dephosphorylation after PA103 infection thereby altering FOXK2 vulnerability to SCFFBXO24 driven degradation." (PMID 38735474, 2024). "While P. aeruginosa (strain PA103) infection of cells reduced FOXK2 protein as the multiplicity of infection (MOI) increased, there was a notable increase in FOXK2 mRNA levels, perhaps representing a compensatory mechanism." (PMID 38735474, 2024). "And, Foxk2 overexpression significantly enhanced adipogenesis following adipogenic treatment, as evidenced by a 24% increase in Oil Red O staining compared to control Ad‐GFP infection." (PMID 39789420, 2025). "Furthermore, we detected integrations within or near STAT5B and FOXK2 genes during acute and/or chronic states, lending support to the notion that clonally expanded sites during ART treatment can be established early during infection." (PMID 32970634, 2020). "In contrast, immunoreactive levels of FOXK2, OPA1, MFF, and PHB1 generally were preserved in the majority of Fbxo24+/− mice regardless of infection." (PMID 38735474, 2024).
bacterial infection (1 paper, 2024). "Proteomic analysis of FOXK2 pull-down revealed its associations with various proteins relevant to mitochondrial activities and cellular defense against viral and bacterial infections." (PMID 38735474, 2024). "In this study, we demonstrate that FOXK2 is depleted in lung epithelial cells after bacterial infection and that the transcription factor is targeted for disposal in cells by the SCFFBXO24 ubiquitin E3 ligase." (PMID 38735474, 2024). "Further, we executed experiments in which we overexpressed Flag-FOXK2 with or without FBXO24-V5 followed by bacterial infection." (PMID 38735474, 2024).
metabolic disorders (1 paper, 2024). "Dysfunction of these FOXK2-involving processes is associated with the pathogenesis of various human diseases, including tumors and metabolic disorders." (PMID 38741782, 2024). "FOXK1 and FOXK2, the two members of the FOXK subfamily, have gained attention only in recent years, particularly in the context of tumors and metabolic diseases." (PMID 38741782, 2024). "Additionally, FOXK2’s involvement in intracellular insulin signaling via the AKT/mTOR pathway suggests its potential role in regulating various metabolic pathways such as glycolysis and cholesterol biosynthesis, which are crucial in diabetes and other metabolic disorders." (PMID 38741782, 2024).
FOXK2 also shares sentences with these, for which no sentence is quoted: osteosarcoma (2 papers); Age-related cataract (1); anorectal malformation (1); bladder urothelial carcinoma (1); cholangiocarcinoma (1); colon adenocarcinoma (1); Congenital ptosis (1); Cutaneous T-Cell Lymphoma (1); diffuse large B-cell lymphoma (1); endometrial cancer (1); Esophageal atresia (1); esophageal carcinoma (1); glioblastoma (1); head and neck squamous cell carcinoma (1); intestinal atresia (1); lung adenocarcinoma (1); lung squamous cell carcinoma (1); male infertility (1); melanoma (1); metastatic melanoma (1); nasopharyngeal carcinoma (1); nervous system tumors (1); neurodevelopmental disorder (1); pancreatic cancer (1); peripheral T-cell lymphoma (1); prostate adenocarcinoma (1); renal carcinoma (1); renal cell carcinoma (1); skeletal muscle disorder (1); uterine corpus endometrial carcinoma (1).
A further 1 disease shares a sentence with FOXK2 in 1 paper.